RNU6-680P (RNA, U6 small nuclear 680, pseudogene)
Gene: Small nuclear RNA gene on chromosome 5 (75,709,495 to 75,709,599, reverse strand). Ensembl gene ENSG00000207333.
Homologues: Orthologues: chimpanzee U6 (98% identical), macaque U6 (89% identical). Paralogues in human: RNU6-140P (89% identical), RNU6-1029P (88% identical), RNU6-12P (87% identical), RNU6-13P (87% identical), RNU6-25P (87% identical), RNU6-32P (87% identical), RNU6-33P (87% identical), RNU6-41P (87% identical), RNU6-44P (87% identical), RNU6-49P (87% identical), RNU6-820P (87% identical), RNU6-1 (86% identical), and 1287 more.